MRPL44 (mitochondrial ribosomal protein L44)
Description:
Component of the 39S subunit of mitochondrial ribosome. May have a function in the assembly/stability of nascent mitochondrial polypeptides exiting the ribosome.
Synonyms: L44mt; MRP-L44; FLJ12701; FLJ13990; mL44; COXPD16
Tractability: Small molecule: a structure with a bound ligand is known. Antibody: its Gene Ontology location is reachable by antibodies, with high confidence. PROTAC: ubiquitination databases record sites on it; its protein half-life has been measured.
Gene: Protein-coding gene on chromosome 2 (223,957,403 to 223,969,078, forward strand). Ensembl gene ENSG00000135900.
Subcellular location: Mitochondrion; Mitochondrion matrix
Subcellular location (Human Protein Atlas): Mitochondria; Nuclear bodies; Nucleoplasm; Plasma membrane
Pathways (Reactome):
Metabolism of proteins: Mitochondrial ribosome-associated quality control; Mitochondrial translation elongation; Mitochondrial translation initiation; Mitochondrial translation termination
Gene Ontology:
Molecular function: protein binding; RNA binding; ribonuclease III activity; double-stranded RNA binding
Biological process: mitochondrial translational elongation; mitochondrial translation; RNA processing
Cellular component: mitochondrial large ribosomal subunit; mitochondrion; mitochondrial inner membrane; mitochondrial matrix
Genetic constraint (gnomAD): Loss-of-function variants: 20 observed, 24.34 expected, observed/expected ratio (o/e) 0.82, 90% interval 0.58 to 1.19. The upper end of that interval is the gene's LOEUF score, 1.19, which puts it in group 5 of 6, group 1 being the genes least tolerant of losing a copy. Missense variants: 394 observed, 404.56 expected, observed/expected ratio (o/e) 0.97, 90% interval 0.9 to 1.06. Synonymous variants: 165 observed, 156.96 expected, observed/expected ratio (o/e) 1.05, 90% interval 0.93 to 1.2.
Gene-disease validity (ClinGen):
ClinGen rates the evidence that MRPL44 causes each of these diseases.
mitochondrial disease (autosomal recessive): Definitive.
Homologues: Orthologues: chimpanzee MRPL44 (99% identical), macaque MRPL44 (97% identical), dog MRPL44 (91% identical), rabbit MRPL44 (90% identical), guinea pig MRPL44 (89% identical), pig MRPL44 (88% identical), rat Mrpl44 (87% identical), mouse Mrpl44 (86% identical), tropical clawed frog mrpl44 (55% identical), zebrafish mrpl44 (55% identical), Drosophila melanogaster mRpL44 (33% identical), Caenorhabditis elegans mrpl-44 (24% identical).
Diseases named in the same sentence as MRPL44 in open-access papers:
MRPL44 is named in the same sentence as 21 diseases in open-access papers, as found by Europe PMC text mining. Sharing a sentence is not in itself a finding about the gene and the disease. The quoted sentences say what the papers report.
hypertrophic cardiomyopathy (4 papers, 2018 to 2024). A condition in which the myocardium is hypertrophied without an obvious cause. "Mutation of the human MRPL44/mL44 gene has been reported to be directly linked to childhood-onset hypertrophic cardiomyopathy and progressive multi-system disease." (PMID 38950860, 2024). "mL44 (MRPL44)—The c.467T > G (p.Leu156Arg) mutation in mL44 was identified in multiple unrelated patients presenting with childhood-onset hypertrophic cardiomyopathy and additional neurological and neuro-ophthalmological symptoms manifesting in adulthood." (PMID 33917098, 2021). "MRPL44 associated with cardiomyopathy has reported that MRPL44 had mutation c.467T>G, (p.Leu156Arg) and c.233G>A, (p.Arg78Gln) in two unrelated patients with childhood hypertrophic cardiomyopathy." (PMID 33238645, 2020).
cardiomyopathy (3 papers, 2020 to 2024). A disease of the heart muscle or myocardium proper. "The MRPL44 mutation was one of the important causes of cardiomyopathy and it resulted in mitochondrial cardiomyopathy in human infants, which is based on the analysis of 66 myocardial cases in the Finnish heart transplant center." (PMID 33238645, 2020). "Similarly, variants in MRPL44 are known to cause cardiomyopathy." (PMID 37148394, 2023).
papillary thyroid cancers (2 papers, 2021 to 2022). "MRPL44 expression was identified as a predictor of lymph node metastasis in papillary thyroid carcinoma, and MRPL13 inhibition was shown to be a key upstream regulator of OXPHOS dysfunction and hepatoma cell invasiveness." (PMID 36233293, 2022). "illustrated that expression of MRPL44 (components of MRPs) was significantly related to lymph node metastasis and influenced OXPHOS in papillary thyroid cancers (PTCs)." (PMID 34026630, 2021).
Allergy (1 paper, 2019). An allergy is an immune response or reaction to substances that are usually not harmful. "Gene-based analyses identified NRP2, MRPL44 and SERPINE2 to be associated with various asthma and allergy-related traits." (PMID 30206357, 2019).
lung carcinoma (1 paper, 2021). "Furthermore, MRPL44 and MRPL12 were both members of mitochondrial ribosomal proteins, whose abnormal expression was found associated with the tumorigenesis and development of lung cancer." (PMID 34760888, 2021).
cancer (3 papers, 2019 to 2023). A tumor composed of atypical neoplastic, often pleomorphic cells that invade other tissues. "The CpG in the 3′ UTR of MRPL44, which showed cancer-hypermethylation in Health ABC, showed hypermethylation in the Roos cohort at p-value = 0.08." (PMID 31149338, 2019). "Compared with control cell lines (BEAS-2B), MRPL44 and CYCS were significantly higher expressed in cancer cell lines (A549 and H1299), while CAT was significantly lower expressed." (PMID 36798829, 2023).
tumor (2 papers, 2024 to 2025). "In thyroid cancer, patients with unaltered MRPL44 expression between tumour and benign tissue were observed to have an increased risk of lymph-node metastasis compared to those with decreased expression in tumour tissue." (PMID 39354291, 2024). "Similarly, one study observed a correlation between high MRPL44 expression and an increased risk of tumour recurrence in breast cancer." (PMID 39354291, 2024). "Its mRNA and protein were enriched in the tumor samples, and a higher level of the mRNA was related to poorer prognosis, indicating that MRPL44 is a tumor-promoting gene, and its autoantibody may play an anti-tumor role." (PMID 39949782, 2025). "Among them, the expression of TIPRAP, WSCD1, TCP11L2, DPP4, CAB39 and PDPK1 were down-regulated, while PARP1, DEPDC1B, CKAP2, ORMDL2, MRPL44, POLD4 and TMEM187 were increased in tumor group." (PMID 39949782, 2025).
mitochondrial disease (1 paper, 2022). "Mitochondrial disease-causing mutations were found in thirteen small ribosomal subunit mitoribosomal proteins (MRPS1, MRPS2, MRPS6, MRPS7, MRPS9, MRPS11, MRPS14, MRPS16; MRPS22, MRPS23, MRPS25, MRPS34, MRPS39) and four large ribosomal mitochondrial proteins (MRPL3, MRPL12, MRPL24, MRPL44)." (PMID 36140315, 2022).
neurodegenerative disease (1 paper, 2025). A disorder of the central nervous system characterized by gradual and progressive loss of neural tissue and neurologic function. "In addition to further highlighting the role of the mitochondrial translation, this result is in line with evidence that the absence or defects in MRPL44 are associated with neurodegenerative diseases in humans, including PD." (PMID 40194557, 2025).
neurodevelopmental disorder (1 paper, 2022). A behavioral and cognitive disorder with onset during the developmental period that involves impaired or aberrant development of intellectual, motor, or social functions. "Five of these genes are already classified as diagnostic grade genes in the IEM panel (COQ4, ELAC2, MRPL44, MSTO1 and SKIV2L) and three others are diagnostic grade genes in different neurology and neurodevelopmental disorder gene panels (EIF2B4, ELP1, EXOSC8)." (PMID 36229886, 2022).
MRPL44 also shares sentences with these, for which no sentence is quoted: Childhood onset (2 papers); asthma (1); cardiac disease (1); chronic kidney disease (1); colorectal cancer (1); deficiencies (1); hepatoma (1); kidney disease (1); Leigh syndrome (1); lymph node metastasis (1); lymphoma (1).